CENPO (centromere protein O)
Description:
Component of the CENPA-CAD (nucleosome distal) complex, a complex recruited to centromeres which is involved in assembly of kinetochore proteins, mitotic progression and chromosome segregation. May be involved in incorporation of newly synthesized CENPA into centromeres via its interaction with the CENPA-NAC complex. Modulates the kinetochore-bound levels of NDC80 complex.
Synonyms: CENP-O; MCM21R; MGC11266; ICEN-36
Tractability: PROTAC: ubiquitination databases record sites on it.
Gene: Protein-coding gene on chromosome 2 (24,793,111 to 24,822,376, forward strand). Ensembl gene ENSG00000138092.
Subcellular location: Nucleus; Chromosome, centromere; Chromosome, centromere, kinetochore
Subcellular location (Human Protein Atlas): Nucleoplasm; Nuclear bodies
Pathways (Reactome):
Cell Cycle: Amplification of signal from unattached kinetochores via a MAD2 inhibitory signal; Deposition of new CENPA-containing nucleosomes at the centromere; EML4 and NUDC in mitotic spindle formation; Mitotic Prometaphase; Resolution of Sister Chromatid Cohesion; Separation of Sister Chromatids
Signal Transduction: RHO GTPases Activate Formins
Gene Ontology:
Molecular function: protein binding
Biological process: chromosome segregation; kinetochore assembly
Cellular component: inner kinetochore; nuclear body; nucleoplasm; cytosol; Mis6-Sim4 complex; nucleus; chromosome, centromeric region; kinetochore
Genetic constraint (gnomAD): Loss-of-function variants: 26 observed, 31.71 expected, observed/expected ratio (o/e) 0.82, 90% interval 0.6 to 1.14. The upper end of that interval is the gene's LOEUF score, 1.14, which puts it in group 4 of 6, group 1 being the genes least tolerant of losing a copy. Missense variants: 309 observed, 328.39 expected, observed/expected ratio (o/e) 0.94, 90% interval 0.86 to 1.03. Synonymous variants: 148 observed, 133.45 expected, observed/expected ratio (o/e) 1.11, 90% interval 0.97 to 1.27.
Homologues: Orthologues: chimpanzee CENPO (99% identical), macaque CENPO (91% identical), dog CENPO (76% identical), pig CENPO (76% identical), guinea pig CENPO (73% identical), mouse Cenpo (67% identical), rat Cenpo (65% identical), rabbit CENPO (62% identical), tropical clawed frog cenpo (38% identical), zebrafish cenpo (24% identical).